DDR2 (discoidin domain receptor tyrosine kinase 2)
Diseases named in the same sentence as DDR2 in open-access papers (continued):
Sharing a sentence is not in itself a finding about the gene and the disease.
breast carcinoma (continued). "We have previously shown that the action of DDR2 in breast cancer CAFs is important for ITGB1 activity." (PMID 35884543, 2022). "Discoidin domain receptor 2 (DDR2) is arising as a promising therapeutic target in breast carcinoma (BC)." (PMID 35711892, 2022). "In order to evaluate the role of DDR2 during BC development, we studied the function of the main genes coexpressed with DDR2 in the mammary tumor tissue." (PMID 35711892, 2022). "DDR2 has also been shown to be a favorable independent predictor of recurrence and outcome in primary breast cancers." (PMID 34207360, 2021). "Pregnancy-associated plasma protein-A (PAPP-A), overexpressed in more than 70% of breast cancers, activates DDR2 converting postpartum anti-proliferative collagen into tumor-promoting collagen." (PMID 34805157, 2021). "Another report showed that DDR2 mediates stromal and cancer cell interaction in mesenchymal stem cells and metastasis growth in breast cancer." (PMID 33718128, 2021). "In breast cancer, DDR2 can induce tumor cell migration and invasion when expressed by tumor cells and/or by CAF or multipotent stromal cells (MSCs)." (PMID 33917302, 2021). "Upregulation of DDR1 promotes migration of breast cancer cells and DDR1 and DDR2 are associated with metastatic breast cancer." (PMID 33670586, 2021). "Whereas DDR1 play a pro-apoptotic role, DDR2 has been shown to have a pro-metastatic role in breast carcinoma." (PMID 35004699, 2021). "Discoidin domain receptor Tyrosine Kinase 2 expression in breast cancer was found to be six times higher than in normal breast tissue, and importantly was a significant independent predictor of both recurrence and prognosis." (PMID 34805157, 2021). "In experimental mouse models of breast cancer, WRG-28 inhibits cancer invasion and migration by targeting DDR2, reduces the supporting effect of the matrix on cancer, and thus inhibits the colonization of metastatic breast cancer cells in the lungs." (PMID 33722297, 2021). "Stage III and IV breast cancer patients have been treated with tyrosine kinase inhibitors (TKIs), including some that inhibit DDR2 (e.g. dasatinib and imatinib), alone and in combination with other therapies." (PMID 34477203, 2021). "DDR2 is a collagen‐binding receptor tyrosine kinase (RTK) critical for breast cancer metastasis through multiple mechanisms including mediating integrin‐mediated mechanotransduction in CAFs,112 and have been found to be abundant in many cancer‐derived EVs." (PMID 33145869, 2021). "Previous in vivo data and data presented herein indicate that, at least in breast cancer cell lines and breast tumors, DDR2 inhibition has little effect on cell proliferation or survival." (PMID 34477203, 2021). "In other words, tumor cell tyrosine kinase-inactive DDR2 supported breast cancer metastasis in vivo." (PMID 34477203, 2021). "DDR2 gene deletion in a breast cancer mouse models has been shown to increase anti-PD-1 therapy sensitivity, and the combination of anti-PD-1 and DDR2 tyrosinase inhibitor Dasatinib reduces tumor burden." (PMID 34805157, 2021). "Beclin-1 (a critical regulator of autophagosome formation) regulates DDR2 expression, reducing both DDR2 expression and pro-inflammatory mediator IL-1β in breast cancer." (PMID 34805157, 2021). "Breast Cancer-Associated Mesenchymal stem/multipotent stromal Cells (BC-MSC) can promote metastasis by increasing collagen deposition, with DDR2 up-regulation reported in MSC’s and in metastatic cancers." (PMID 34805157, 2021). "They functionally observed that Snai1 activation induced by DDR2 increased in vitro migration and invasion and in vivo metastatization of breast cancer cell lines." (PMID 32793478, 2020). "During breast cancer development and progression endogenous DDR2 expression is upregulated in CAFs and appears to be critical for their activation." (PMID 31144616, 2019).
breast carcinoma (continued). "In GEMMs deletion of Ddr2 appears to have a greater impact on breast cancer metastasis than does either α1 or α2 Integrin deletion (two α chains of collagen binding integrins), while β1 Integrin plays a critical role in tumor initiation and maintenance." (PMID 31144616, 2019). "The role of DDR2 in PAPP-A-driven PABC adds to the growing evidence of the importance of DDR2 in breast cancer metastasis and that it is active in both tumor and stromal cells." (PMID 31046834, 2019). "A recent report described a novel signaling role for DDR2 in breast cancer metastasis through the stabilization of the epithelial to mesenchymal transition (EMT) transcription factor Snail." (PMID 31046834, 2019). "In both these models the action of a cell surface fibrillar collagen receptor DDR2 in tumor cells and tumor stromal cells has been shown to regulate breast cancer metastasis." (PMID 31144616, 2019). "In breast cancer, MEK inhibition resulted in acute ERK activity loss and subsequent c-MYC degradation that induced expression and activation of PDGFRB, DDR2 and VEGFR272, an RTK combination found in patients 6 (PT) and 10 (M) of our dataset." (PMID 29743718, 2018). "Lately, it has been showed that DDR2 expression and activation in breast cancer cells can be increased by hypoxia, which is well-known to participate in tumor metastatic events." (PMID 27014069, 2016). "While in breast cancer cells, Zhang and co-workers showed that activation of DDR2 regulates SNAIL1 protein stability by stimulating ERK2 activity, in a Src-dependent manner." (PMID 27014069, 2016). "Discoidin domain receptor 2 (DDR2) facilitates the metastasis of breast cancer through ERK-mediated Snail1 phosphorylation." (PMID 26759750, 2016). "Recently, it was shown that the type I collagen can activate DDR2/ERK2/SNAIL1 signaling axis in breast cancer." (PMID 26362312, 2015). "Recent work has also indicated that overexpression of DDR2 contributes to breast cancer invasion and lymph node metastasis." (PMID 25955408, 2015). "Recently, it was shown that collagen I can activate DDR2/ERK2/SNAIL1 signaling axis in breast cancer." (PMID 26362312, 2015). "In breast cancer, the inactivation of DDR2′s tyrosine kinase activity mediates metastasis in vivo." (PMID 40563472, 2025). "In breast cancer, DDR2 knockdown inhibits tumor cell proliferation and invasiveness." (PMID 40563472, 2025). "Knockdown of DDR2 in breast cancer cells reduces glutamine and aspartate synthesis." (PMID 40563472, 2025). "It is therefore hypothesized that DDR2 contributed to breast cancer chemoresistance independently of the apoptosis of breast cancer cells." (PMID 39766183, 2024). "Moreover, in vitro experiments demonstrated that DDR2 promoted the proliferative activity of breast cancer cells, and cell viability after epirubicin treatment was significantly maintained by DDR2 in a collagen I-dependent manner." (PMID 39766183, 2024). "However, it has been interestingly reported that the expression of DDR2 is elevated in breast cancer tissues compared to normal breast tissues, whereas that of DDR1 is decreased in breast cancer tissues." (PMID 39766183, 2024). "Previous studies have shown that DDR2 is involved in the communication between tumor cells and stromal cells in breast cancer, and its selective extracellular small molecule inhibitor (WRG-2) can delay tumor invasion and migration by inhibiting receptor–ligand interactions." (PMID 38280909, 2024). "We next examined the expression of the DDR2 gene in a panel of breast cancer cell lines." (PMID 36713812, 2022). "DDR2 has also been shown to mediate hypoxia-induced EMT in breast cancer cells." (PMID 36713812, 2022). "In addition, Liu inhibited the progression of estrogen receptor-positive breast cancer by constructing MiR-4458-loaded gelatin nanospheres targeting COL11A1 to block the DDR2/SRC signaling pathway." (PMID 36160004, 2022).
breast carcinoma (continued). "Of particular interest, DDR2 has been demonstrated to stabilise Snail1 protein in breast cells and a significant association Snail1, lack of E-cadherin and presence of DDR2 expression was observed in samples of human breast cancer." (PMID 35406381, 2022). "Likewise, DDR2 is also overexpressed in acute myelocytic leukemia, thyroid cancer, cholangiocarcinoma, Hodgkin’s lymphoma, breast cancer, and nasopharyngeal carcinoma." (PMID 35267698, 2022). "DDR2 showed preferential expression in the basal-b subtype of breast cancer cell lines." (PMID 36713812, 2022). "Moreover, DDR2 overexpression correlated with a higher CAFs and TAMs infiltration into the mammary tumor tissue." (PMID 35711892, 2022). "Furthermore, hypoxia upregulates DDR2 expression to induce Snail expression and breast cancer metastasis." (PMID 34065317, 2021). "Furthermore, HSP47 silencing can reduce the stability of DDR2, and inhibit the migration and invasion of (breast) cancer cells." (PMID 34805157, 2021). "In summary, we believe we have shown that tyrosine kinase-independent actions of DDR2 in breast tumor cells and breast tumor CAFs contribute to metastatic regulation of breast cancer, in particular through regulation of the secretome (i.e. paracrine regulation)." (PMID 34477203, 2021). "Furthermore, this team demonstrated that DDR2, when expressed by stromal cells, promotes the metastatic spread of breast cancer cells." (PMID 32984031, 2020). "Recently, DDR2 was reported to be critical for breast cancer invasion and migration in vitro and for metastasis in vivo via sustaining SNAIL1 stability and activity to promote tumor cells migration and invasion through collagen-I-enriched tumour-associated matrices." (PMID 24885564, 2014). "In addition, accumulating studies have indicated the protumor roles of DDR2 in breast cancer." (PMID 39766183, 2024). "DDR2 could be a poor prognostic factor in breast cancer patients." (PMID 39766183, 2024). "Interestingly, DDR2 seems to also play a role in breast cancer EMT." (PMID 35004699, 2021). "To determine whether the partial effects of tyrosine kinase-inactive DDR2 in tumor cells was relevant in vivo, we generated Balb/c-derived 4T1 mouse mammary tumor cell lines depleted of DDR2 (using shRNA) and lines rescued with species-specific WT, K608E or ΔKD DDR2 isoforms." (PMID 34477203, 2021). "Finally, they demonstrated that breast cancer cell lines with an invasive phenotype frequently and overexpressing DDR2 associated with nuclear-activated Snai1 and absence of E-cadherin." (PMID 32793478, 2020). "This study underscores how DDR2 and integrins differentially transduce mechanical cues from ECM, ultimately shaping breast cancer cell behavior and proliferative capacity." (PMID 41492134, 2026). "DDR2/STAT1/P27 signaling responds to ECM-derived mechanical forces, inducing cell cycle arrest in breast cancer cells." (PMID 40563472, 2025). "DDR2 has been shown to promote proliferation in several cancers, including melanoma, gastric cancer, HCC, lung cancer, breast cancer, and ovarian cancer." (PMID 40563472, 2025). "In breast cancer, biomechanical forces induced by the ECM promote tumor cell dormancy through DDR2 (discoidin domain receptor 2)/STAT1 signaling." (PMID 39682769, 2024). "Discoidin domain receptor 2 (DDR2) is activated by collagens and plays important roles in human breast cancer." (PMID 39766183, 2024). "K14+ breast cancer cells expression DDR2 and CXCR4 and CAFs expressing DDR2 guides metastasis from primary tumor organoids to polarize to the leading edge and direct migration." (PMID 36906534, 2023). "DDR2 was shown to regulate SNAI1 stability through stimulating ERK2 activity and thereby facilitate breast cancer metastasis." (PMID 36713812, 2022). "DDR2 expression was also independently correlated with FOXQ1 and SNAI1 across TCGA breast cancer data." (PMID 36713812, 2022).
breast carcinoma (continued). "Another inhibitor WRG-28 regulates DDR2, targeting the RTK extracellular domain, inhibiting the invasion of breast cancer cell migration." (PMID 34805157, 2021). "Overexpression of DDR2, through ERK2/Snail signaling, increases MT1-MMP and MMP2 expression in hepatocellular carcinoma and MT1-MMP expression in breast cancer." (PMID 33917302, 2021). "Type I collagen activated DDR2 increases the stability of the EMT driving factor SNAIL1, promoting invasion and migration of breast cancer cells in vitro and metastasis in vivo." (PMID 34805157, 2021). "In a previous study, we have examined this correlation in multiple breast cancer cell lines, by analyzing expression levels of E-cadherin, vimentin, DDR1, DDR2, MT1-MMP, and BIK mRNAs in 58 breast cancer cell lines." (PMID 31130862, 2019). "In addition to offering a potentially important link between several known factors of breast cancer risk, our current study also identifies novel functions of PAPP-A, namely the elevation of collagen through LARP6 and the activation of the collagen receptor DDR2." (PMID 31046834, 2019). "Recently, it was reported that DDR2 stabilized SNAIL1 to reduce E-cadherin protein levels and promoted the EMT in breast cancer cells." (PMID 26934957, 2016). "In cancer, dual blockade of DDR2 and Intαv subfamily (ITGAV) via siRNA-loaded nanocarriers has been pursued as a strategy to overcome matrix barriers to enhance immune infiltration in preclinical models of breast cancer." (PMID 41492134, 2026). "The fact that DDR2 depletion reduced in vivo metastases imply not redundant role during breast cancer metastasis." (PMID 41492134, 2026). "Notably, the discoidin domain receptor tyrosine kinase 2 (DDR2), induced by EMT regulators TWIST and SNAIL, exhibits elevated expression levels in mesenchymal breast cancer cells." (PMID 38140764, 2024). "The results of our current study provide new insights into the cancer-driving function of DDR2, suggesting that DDR2, as a shared effector of the EMT program, may drive tumor progression by promoting breast cancer cell motility and metabolic reprogramming." (PMID 36713812, 2022). "In a different study, Grither et al111 utilized WRG28, a small molecule inhibitor of discoidin domain receptor 2 (DDR2) extracellular domain, to suppress tumour‐microenvironment interaction, tumour invasion, and further lung metastatic colonization by breast cancer cells." (PMID 33145869, 2021). "Nevertheless, DDR2 was found to be required for collagen I-mediated activation of MT1-MMP in fibroblast but not in fibrosarcoma or in breast cancer." (PMID 33917302, 2021). "Investigating DDR2 signaling pathways, the collagen-dependent protease pappalysin-1 (PAPP-1) plays a critical role in postpartum breast cancer, with increased IGF signaling resulting from PAPP-1-mediated degradation of IGFBP-4 and IGFBP-5, promoting DDR2 signaling." (PMID 34805157, 2021). "The effect of reciprocal bone marrow transplantation of WT bone marrow into in Ddr2-/-; MMTV-PyMT mice or Ddr2-/- bone marrow into WT MMTV-PyMT mice upon breast cancer metastasis and primary tumor ECM architecture and mechanical properties will address this possibility." (PMID 31144616, 2019). "Among them, DDR2 plays an indispensable role in a series of hypoxia-induced behaviors of breast cancer cells, such as migration, invasion, and epithelial-mesenchymal transition (EMT), the activated DDR2 can promote the metastasis of breast cancer." (PMID 30906311, 2019). "The expression levels of E-cadherin, vimentin, DDR1, DDR2, α2 integrin, α11 integrin, COL1A1, MT1-MMP, BIK, estrogen receptor α, progesterone receptor, and HER2 mRNAs in 58 breast cancer cell lines were analyzed in silico, by using the Broad-Novartis Cancer Cell Line Encyclopedia (CCLE) database." (PMID 31130862, 2019). "In some of the basal-like breast carcinoma cells, it has been reported that the low level of DDR1 expression could be compensated by an increase in DDR2 expression." (PMID 31130862, 2019).
breast carcinoma (continued). "Moreover, downregulation of beclin-1 decreased DDR2 expression, which was recently shown to be critical for stabilizing SNAIL1 to promote breast cancer invasion and lymph node metastasis." (PMID 25955408, 2015). "However, the possible involvement of the DDR2/collagen type I axis in breast cancer chemoresistance has not been elucidated." (PMID 39766183, 2024). "Therefore, we also examined whether DDR2 plays a role in HT1080 human fibrosarcoma cells and MDA-MB231 human breast cancer cells." (PMID 28270508, 2017). "In conclusion, targeting the DDR2-SRC-AKT3 axis with dasatinib represents a promising approach for the chemoprevention and chemotherapy of gastric and breast cancers lacking E-cadherin." (PMID 35406381, 2022). "This DDR2-mediated mechanism is only present in non-transformed mesenchymal cells as collagen-induced MT1-MMP activation in HT1080 fibrosarcoma cells and MT1-MMP function in MDA-MB231 breast cancer cells were not affected by DDR kinase inhibition." (PMID 28270508, 2017). "In contrast, DDR2 triggers p38 and ERK1/2 (but not JNK) to activate MMP-13 expression in chondrocytes, p38 and JNK (but not ERK1/2) to activate IL-12 production, ERK2 in breast cancer cells, and p38 MAP kinase or ERK1/2 to activate transcription factor Runx 2 during osteoblast differentiation." (PMID 35267698, 2022).